CTAG1A (cancer/testis antigen 1A)
Synonyms: CT6.1; LAGE-2; ESO1; LAGE2A; NY-ESO-1
Gene: Protein-coding gene on chromosome X (154,585,133 to 154,586,816, forward strand). Ensembl gene ENSG00000268651.
Subcellular location: Cytoplasm
Subcellular location (Human Protein Atlas): Golgi apparatus; Vesicles
Gene Ontology:
Molecular function: identical protein binding; protein binding
Biological process: tRNA threonylcarbamoyladenosine metabolic process
Cellular component: cytoplasm
Homologues: Orthologues: rat Ctag2l1 (31% identical), mouse Ctag2l1 (29% identical), mouse Ctag2l2 (28% identical), rat Ctag2l2 (28% identical), mouse Ctag2 (26% identical), rat Ctag2 (24% identical), tropical clawed frog lage3 (19% identical), Drosophila melanogaster Tcs6 (13% identical). Paralogues in human: CTAG1B (100% identical), CTAG2 (86% identical), LAGE3 (34% identical).
Diseases named in the same sentence as CTAG1A in open-access papers:
CTAG1A is named in the same sentence as 11 diseases in open-access papers, as found by Europe PMC text mining. Sharing a sentence is not in itself a finding about the gene and the disease. The quoted sentences say what the papers report.
lung carcinoma (4 papers, 2014 to 2025). "Four known biomarkers (CHEK2 in both plasma and urine, CDKN1B, PCNA, and THBS1) were identified as false positives (red) in our breast cancer list, and seven (KRAS, GDNF in both breastmilk and plasma, MYCL1 in both blood and serum, CD40LG, CGA, CTAG1A, ERCC6, and HRAS) in our lung cancer list." (PMID 25379168, 2014).
adenoma (1 paper, 2021). A neoplasm arising from the epithelium. "Using the Sengenics CTA protein array, pooled benign controls (n = 2, adenomas) showed detectable autoantibodies (Z-score > 3) against five antigens (AURKA, CTAG1A, CYP450 3A4, MAGEA4 and RAF1)." (PMID 34681879, 2021).
coronary heart disease (1 paper, 2024). "This study focuses on four biomarkers C5orf58, ZNF180, CTAG1A, and IL13RA1 that are associated with M1 macrophage polarization and bubble cell proliferation in coronary heart disease, highlighting their key roles in the pathogenesis of the disease." (PMID 39723414, 2024). "In this study, CTAG1A, as one of the cancer/testicular antigen related genes, was screened as a biomarker for coronary heart disease." (PMID 39723414, 2024). "This study focuses on the roles of C5orf58, ZNF180, CTAG1A, and IL13RA1 in the polarization of M1 macrophages and the increase of bubble cells in coronary heart disease." (PMID 39723414, 2024).
glioma (1 paper, 2024). A benign or malignant brain and spinal cord tumor that arises from glial cells (astrocytes, oligodendrocytes, ependymal cells). "We assessed the pharmacological mechanism of DAC to induce NY-ESO expression in glioma via the reversal of this hypermethylation profile in the CTAG1A/B CpG Island." (PMID 38856710, 2024).
melanoma (1 paper, 2021). A malignant, usually aggressive tumor composed of atypical, neoplastic melanocytes. "Arguably, the prototype CTAg is NY-ESO-1 (CTAG1A or identical gene copy CTAG1B), which induces spontaneous cellular and humoral immune responses in melanoma and other cancers." (PMID 33918976, 2021). "The expression of differentiation antigens that are commonly present and have been previously used as immunological targets in melanoma, namely, TYR (tyrosinase) and MLANA (Melan-A/MART1), were compared with CTAG1A and ROPN1 or ROPN1B in our panel of melanoma cell lines." (PMID 33918976, 2021). "We assessed expression of ROPN1B, NY-ESO-1 (single protein from CTAG1A or CTAG1B genes), MLANA and SOX10 (used here as a melanoma tumour marker) at the protein level by multispectral immunohistochemistry on melanoma tissue microarrays (TMAs) comprising two or three cores from 61 patient tumours." (PMID 33918976, 2021). "We further evaluated the gene expression levels of ROPN1, ROPN1B, CTAG1B (identical gene copy to CTAG1A for which no gene expression data is available), TYR and MLANA in 472 additional melanoma samples using data accessible via The Cancer Genome Atlas (TCGA)." (PMID 33918976, 2021).
multiple myeloma (1 paper, 2016). "The cancer testis antigen 1 A (CTAG1A, also known as CTAG1B/NY-ESO-1) peptide SLLMWITQC in complex with HLA-A*02:01 is an active target for engineered T-cell based therapy in multiple myeloma, synovial sarcoma, and advanced melanoma." (PMID 27439771, 2016).
ovarian tumor (1 paper, 2023). "Lower levels of mRNA expression of genes of the 21 CTAs in ovarian tumors were detected for CTAG1A, CTAG1B, MAGEC1, and PIWIL2." (PMID 37835834, 2023). "For ovarian tumor samples, we detected six hub genes: GAGE2A, GAGE1, MAGEA9, CTAG1A, CTAG1B, and MAGEA1." (PMID 37835834, 2023).
cancer (11 papers, 2015 to 2025). A tumor composed of atypical neoplastic, often pleomorphic cells that invade other tissues. "Cancer/Testis Antigen 1A (CTAG1A) is a protein coding gene associated with cancer and is a member of the Cancer Testis Antigen (CTA) family." (PMID 39723414, 2024). "The other protein identified by the “protein scoring” workflow was CTAG1A, which is a cancer testis antigen." (PMID 37634036, 2024). "We loaded ImmDCs and MaDCs from three donors with a mixture of equal amounts of seven long peptides (25–40 mers) from the known cancer associated antigens PMEL, MAGEA4, MLANA, and CTAG1A (NY-ESO1)." (PMID 32983136, 2020). "CTAG1A is a known tumor cell antigen found in various types of cancers." (PMID 29021294, 2017). "Out of these, FMR1NB, CTAG1A and MAGEA9B are cancer/testis antigens." (PMID 25884295, 2015). "In contrast, the HDACi TSA triggered CTAG1A expression in Caco-2 cells but not in HCT116 cells at a similar dose, showing that not all cancers react to the same treatment." (PMID 36355490, 2022).
tumor (4 papers, 2016 to 2025). "The examination indicated the hub genes in tumor samples, including GAGE2A, GAGE1, MAGEA9, CTAG1A, CTAG1B, and MAGEA1; and the hub genes in healthy ovarian tissue samples, including SPA17, MAGEC1, KDM5B, SSX4, and MAGEA9." (PMID 37835834, 2023). "This has, for example, been shown for Yersenia pestis, Plasmodium yoelii, dengue virus, HIV, the cancer/testis antigen 1A (known as CTAG1A or NY-ESO-1), or the Her2/neu breast cancer antigen in a protective model with NT2.5 tumor cells." (PMID 27043640, 2016). "The analysis of the mRNA expression levels of 21 CTAs in healthy and tumor ovarian tissue showed an up-regulation in the expression level of AKAP3, MAGEA4, PIWIL1, and PRAME in tumor samples and a down-regulation in the expression level of CTAG1A, CTAG1B, MAGEC1, and PIWIL2." (PMID 37835834, 2023).
CTAG1A also shares sentences with these, for which no sentence is quoted: breast carcinoma (1 paper); metastatic cancers (1).